ZNF791 (zinc finger protein 791)
Description:
May be involved in transcriptional regulation.
Synonyms: FLJ90396
Tractability: PROTAC: ubiquitination databases record sites on it.
Gene: Protein-coding gene on chromosome 19 (12,610,918 to 12,633,840, forward strand). Ensembl gene ENSG00000173875.
Subcellular location: Nucleus
Subcellular location (Human Protein Atlas): Nucleoplasm
Pathways (Reactome):
Gene expression (Transcription): Generic Transcription Pathway
Gene Ontology:
Molecular function: protein binding; DNA-binding transcription factor activity, RNA polymerase II-specific; RNA polymerase II transcription regulatory region sequence-specific DNA binding
Biological process: regulation of transcription by RNA polymerase II; regulation of DNA-templated transcription
Cellular component: nucleus
Genetic constraint (gnomAD): Loss-of-function variants: 3 observed, 8.27 expected, observed/expected ratio (o/e) 0.36, 90% interval 0.16 to 0.94. That is too few expected variants to judge how well the gene tolerates losing a copy. Missense variants: 534 observed, 698.24 expected, observed/expected ratio (o/e) 0.76, 90% interval 0.71 to 0.82. Synonymous variants: 204 observed, 225.57 expected, observed/expected ratio (o/e) 0.9, 90% interval 0.81 to 1.02.
Homologues: Orthologues: chimpanzee ZNF791 (99% identical), macaque ZNF791 (94% identical), rat Zfp791 (66% identical), mouse Zfp791 (64% identical). Paralogues in human: ZNF709 (63% identical), ZNF433 (59% identical), ZNF14 (58% identical), ZNF44 (56% identical), ZNF700 (55% identical), ZNF441 (55% identical), ZNF823 (54% identical), ZNF799 (54% identical), ZNF443 (54% identical), ZNF878 (53% identical), ZNF442 (52% identical), ZNF563 (41% identical), and 3 more.
Diseases named in the same sentence as ZNF791 in open-access papers:
ZNF791 is named in the same sentence as 3 diseases in open-access papers, as found by Europe PMC text mining. Sharing a sentence is not in itself a finding about the gene and the disease. The quoted sentences say what the papers report.
myocardial infarction (1 paper, 2022). Gross necrosis of the myocardium, as a result of interruption of the blood supply to the area, as in coronary thrombosis. "Oxidative stress following myocardial infarction could be accelerated via the KCNQ1OT1/miR-130a-3p/ZNF791 axis." (PMID 36278219, 2022).
prostate carcinoma (1 paper, 2014). A carcinoma that arises from epithelial cells of the prostate gland. "Specifically, ZNF791, whose expression is regulated by rs2861405 through eQTL, encodes a member of the zinc finger protein family that have been reported as associated with prostate cancer at gene expression and protein levels." (PMID 25026280, 2014).
Sepsis (1 paper, 2021). Sepsis is defined as life-threatening organ dysfunction caused by a dysregulated host response to infection. "Our findings suggest that transcription factor such as Crel, NF-kB65, Znf791, Cebpb and miR-649 might regulate most DEGs of capEC during sepsis." (PMID 34638535, 2021).